G6PD (glucose-6-phosphate dehydrogenase)
Diseases named in the same sentence as G6PD in open-access papers (continued):
Sharing a sentence is not in itself a finding about the gene and the disease.
cancer (continued). "miR-1 overexpression in HP75 and MMQ cells transfected with miR-1 mimics represses cell proliferation by targeting G6PD to suppress the PPP and inhibit the glucose metabolism of cancer cells." (PMID 34564317, 2021). "G6PD is also affected by NADP+ levels, which tend to increase during cancer as a result of higher ROS levels and oxidative stress." (PMID 33946927, 2021). "High levels of G6PD expression were observed in human livers infected with HBV and HBV-related cancers, which provides further confirmation of the findings presented here." (PMID 34150630, 2021). "Glucose‐6‐phosphate dehydrogenase (G6PD), the rate‐limiting enzyme of the PPP, is elevated in many cancers and contributes to tumour growth by producing ribose‐5‐phosphate and NADPH through PPP." (PMID 33630390, 2021). "The increased enzymatic expression of G6PD, a central enzyme of the oxidative branch of the PPP, has been reported in a wide variety of cancer types." (PMID 34827081, 2021). "Many studies have reported that the aberrant activation of G6PD or H6PD is related to tumorigenesis and malignancy in rapidly growing cancer cells." (PMID 33723244, 2021). "Considering the pivotal role of G6PD, the rate-limiting enzyme of PPP, in glucose flux redirection and cancer cell proliferation, we then assessed its activity in Pol ι differentially expressed ESCC cell lines." (PMID 34354953, 2021). "In view of the pro-oncogenic role of these proteins, it is noteworthy, that G6PD, MAPK13, PNCK, SLC16A3, and SLC2A1 are among the candidate cancer genes identified by forward genetic screens in mice." (PMID 33427197, 2021). "Mechanistically, KRT6A overexpression is sufficient to upregulate glucose-6-phosphate dehydrogenase (G6PD) levels and increase the pentose phosphate pathway flux, an essential metabolic pathway to support cancer cell growth and invasion." (PMID 34235156, 2021). "The study revealed that the PPP pathway supplies cancer cells with ribose 5-phosphate and NADPH and is regulated by the rate-limiting glucose-6-phosphate dehydrogenase (G6PD) enzyme." (PMID 34638933, 2021). "The G6PD, PGD, TKT, and TALDO1 support glucose flux and generate purines, which are building blocks of DNA and RNA, which help to accelerate proliferation in cancer cells." (PMID 33922165, 2021). "In our study, the metabolic disorder in NSCLC was demonstrated by elevated expression levels of G6PD and SDHA in carcinoma tissues than in paired para-carcinoma tissues." (PMID 34150616, 2021). "Cancer cells display elevated levels and activity of PPP enzymes involved in oxidative PPP, namely glucose 6-phosphate dehydrogenase (G6PD)." (PMID 32408513, 2020). "These miRNAs normally inhibit TKDT and G6PD genes, and their repression by HDAC4 through NRF2 supports cancer cells growth." (PMID 32106613, 2020). "Wnt/c-MYC and p65-NFkB pathways induce the expression of G6PD, activating PPP as part of a more metastatic and chemoresistant cancer phenotype." (PMID 32714858, 2020). "Snail, an important transcription factor in embryonic development and cancer progression, is controlled by the AKT/GSK-3β pathway, which was also inactivated after the knockdown of G6PD." (PMID 32719549, 2020). "However, the question why G6PD is over-activated in different types of cancers is largely unknown." (PMID 33041664, 2020). "When the PI3K/Akt signaling pathway is activated, NRF2 directly increases G6PD, 6PGD, TKT, and TALDO expression to enhance metabolic activities and promote cancer cell growth." (PMID 32582032, 2020).
cancer (continued). "Here, we determined that G6PD levels and ribose synthesis were significantly decreased in ZDHHC1 overexpressing cells, suggesting that ZDHHC1 inhibits cancer through the downregulation of G6PD-mediated glucose flux through the PPP." (PMID 32863941, 2020). "Because glucose-6-phosphate dehydrogenase (G6PD) is a gatekeeper of PPP, our observations suggest that G6PD and CPT1 can be used to therapeutically target the metabolic reliance of human cancer on PPP and FAO." (PMID 32487689, 2020). "In our study we observed a significant reduction of both G6PD and TKTL1 after pioglitazone treatment according to their role in cancer cells that often lose the balance of oxidation and antioxidant." (PMID 31027492, 2019). "Overexpression of G6PD correlates with an adverse prognosis and has been pinpointed as a new biomarker in AML as determined by analysis of the cancer genome atlas AML database." (PMID 31500396, 2019). "Interestingly, the inhibition of G6PD may restore sensitivity of cancer cells to chemotherapy." (PMID 29760380, 2018). "We then analyzed the expression of G6PD and p-STAT3 in human RCC and paired adjacent non-cancer renal tissues (n=10) by immunohistochemistry." (PMID 29312589, 2017). "1,25(OH)2D3 appears to engage in complex, and at times paradoxical metabolic programs in cancer cells, such as the activation of AMPK and autophagic signaling, as well as the induction of G6PD and thus possibly the enhancement of the PPP." (PMID 29048387, 2017). "Glucose-6-phosphate dehydrogenase (G6PD) is a key enzyme that generates NADPH to maintain reduced glutathione (GSH), which scavenges reactive oxygen species (ROS) to protect cancer cell from oxidative damage." (PMID 28692052, 2017). "The cancer pathway finder PCR array revealed 9 genes, including ACSL4, BIRC3,CA9, CCL2, FLT1, FOXC2, G6PD, IGFBP3 and SNAI2, with significantly altered expression in the siRNA-treated MCF-7 cells." (PMID 27478411, 2016). "G6PD catalyzes the rate-limiting step of the PPP, perhaps accounting for the increased G6PD levels found here and in many other cancers." (PMID 27861141, 2016). "Targets of NRF2 such as glucose-6-phosphate dehydrogenase (G6PD) and glutamate–cysteine ligase complex modifier subunit (GCLM) have prominent roles in promoting cancer cell survival by neutralizing the toxic effects of oxidative stress." (PMID 26890145, 2016). "In fact, the activity of glucose-6-phosphate dehydrogenase (G6PD), a major PPP enzyme, increases in proliferating cancer cells." (PMID 24738035, 2014). "The results show that the values of genetic heterogeneity found in cancer and histologically healthy tissues of the two patients for both HPRT and G6PD transcripts are statistically similar to each other and different from the controls." (PMID 20186333, 2010). "Studies indicate that glucose-6-phosphate dehydrogenase (G6PD), along with malic enzymes and methylenetetrahydrofolate dehydrogenase 2 (MTHFD2), represents the most pertinent enzymes examined through IHC concerning cancer aggressiveness." (PMID 41710542, 2026). "Similarly, piR-823 increases glucose-6-phosphate dehydrogenase (G6PD) expression, which in turn increases the consumption of glucose by cancer cells while decreasing the amount of intracellular reactive oxygen species (ROS)." (PMID 39102033, 2025). "Thus, G6PD, central to the PPP, is an indispensable enzyme for cancer cell proliferation, working in conjunction with glycolysis." (PMID 41374996, 2025).
cancer (continued). "Moreover, G6PD promotes the production of hepatocyte growth factor (HGF) from tumor mesenchymal stem cells, which regulate tumor microenvironment surrounding cancer cells, via NF-kB activation." (PMID 41374996, 2025). "We identified a robust upregulation of GLUT1 (SLC2A1), a key rate-limiting factor in the transport of glucose in cancer cells, and genes involved in central glucose metabolism (HK2, ENO1, PKM, and LDHA), PPP (G6PD), and de novo serine biosynthesis pathway (PSAT1, PSPH, and SHMT2)." (PMID 40371988, 2025). "The balance between acetylation by lysine acetyltransferase (KAT9, which inhibits G6PD activity), and deacetylation by SIRT2 (which reactivates G6PD) controls PPP flux and the production of cytosolic NADPH, which is essential for redox homeostasis and cancer cell survival under oxidative stress." (PMID 41009654, 2025). "Given that G6PD is one of the primary regulatory factors of ccRCC metabolic disorders and can be manipulated by BANCR, it is currently unclear to what extent BANCR is involved in the metabolic reprogramming of ccRCC or other cancers." (PMID 39894218, 2025). "Glucose 6-phosphate dehydrogenase (G6PD) is the rate-limiting enzyme of the PPP and plays a crucial role in maintaining metabolic homeostasis in various cancer cells, including glucose oxidation, lipid synthesis, nucleotide precursor generation, and redox balance." (PMID 39894218, 2025). "Indeed, ME1 has been found increased in different kinds of cancers as well as IDH1 and glucose-6-phosphate-dehydrogenase (G6PD), likely preserving cancer cells from excessive reactive oxygen species (ROS) levels and in turn damage to molecules and apoptosis." (PMID 39335602, 2024). "A recent study showed that ASP extract effectively reduced the activities of G6PD, LDHA, PKM2, c-Myc, and glutaminase in HepG2 cells, suggesting that ASP may inhibit glycolysis and glutamine metabolism in cancer cells." (PMID 39697544, 2024). "Additionally, increased activation of NRF2 in cancer cells results in elevated expression of enzymes involved in intermediate metabolism, such as transketolase (TKT) and G6PD." (PMID 38247494, 2024). "The results above suggested a negative correlation between G6PD expression and survival time in some types of cancer." (PMID 37601657, 2023). "In addition, glucose-6 phosphate dehydrogenase (G6PD) regulates EMT and metabolic reprogramming in cancer cells." (PMID 37174052, 2023). "G6PD is a rate-limiting enzyme of the PPP, and its expression is elevated in diverse cancers." (PMID 37491277, 2023). "Moreover, the PPP enzymes, among which is the glucose-6-phosphate dehydrogenase (G6PD), are shown to be crucial for cancer prevention and treatment." (PMID 37190196, 2023). "Finally, Cluster 3 is characterized by up-regulation of SLC1A5 and SLC7A5 that promotes cancer cell dependence on glucose and increases the need of cytosolic NADPH sustained by concomitant up-regulation of G6PD." (PMID 36083313, 2023). "Furthermore, in addition to their role in cancer metabolism, RIP140 and G6PD are both involved in fatty acid biosynthesis, but also in oxidative stress and inflammatory responses." (PMID 35806424, 2022). "This correlation suggests that the regulatory mechanism of BRD4 on KEAP1 and G6PD may be beyond SCLC and may exist in a variety of cancers which provides a new basis for overcoming drug resistance to BETis in other cancer types." (PMID 35453346, 2022).
cancer (continued). "However, the amount of HMGA1 protein in cancer tissue correlated with the amount of FOXM1 and G6PD, with which HMGA1 forms a common pathway for transcriptional regulation and which were similarly associated with TNM stage and overall survival." (PMID 35948739, 2022). "However, the amount of HMGA1 protein in cancer tissue was correlated with the amount of FOXM1 and G6PD." (PMID 35805937, 2022). "The overexpression of G6PD influences DNA synthesis, DNA repair, cell cycle regulation, redox equilibrium, proliferation, EMT, invasion and metastasis to provide an advantageous condition for cancer cells." (PMID 35207558, 2022). "Exposure of carcinoma cells to electrophilic molecules or overexpression of NRF2 significantly increased expression of TIGAR, in parallel to the known NRF2 target genes NQO1 and G6PD." (PMID 35163828, 2022). "The expression of G6PD, an enzyme involved in PPP, was also upregulated in the cancer tissue." (PMID 33681091, 2021). "mRNA expression of GK (a rate-limiting enzyme of glycolysis) and G6PD (a rate-limiting enzyme of the pentose phosphate pathway (PPP)) was significantly increased in the cancer tissue compared to noncancer tissue." (PMID 33681091, 2021). "Considering that G6PD usually only operates around 2% of its maximum potential in non-transformed cells while in cancer cells this percentage is significantly higher, it is vital to highlight the key role of G6PD in the proliferation of tumor cells." (PMID 34572981, 2021). "NRF2 plays a crucial role in promoting the proliferation of cancer cells and metabolism process in lung cancer cells, including the direct transcriptional regulation of PPP-related enzymes such as G6PD, PGD, TKT, and TALDO1, which are responsible for NADPH regeneration." (PMID 33922165, 2021). "Especially, it has been reported that G6PD is mainly involved in pentose phosphate pathway, and the lack of G6PD is inversely related to the survival of patients with cancer." (PMID 32596991, 2020). "Suppression of G6PD blocks EMT of OSCC cell lines and reduces lymphatic metastasis in OSCC orthotopic xenograft model, which indicates that targeting G6PD in cancer cells could be an effective therapeutic strategy." (PMID 32719549, 2020). "In agreement with this hypothesis, G6PD- or H6PD-siRNA simultaneously decreased both d-ribose concentration and culture growth in all studied cancer cell lines." (PMID 33335166, 2020). "Therefore, G6PD, 6PGD, and TKT are promising targets in the PPP for prevention and treatment of metabolic diseases and cancer." (PMID 32582032, 2020). "Additionally, aberrant NRF2 activation in cancer cells leads to remarkably increased expression of TKT and G6PD metabolic enzymes that contribute to metabolic reprogramming and cell proliferation." (PMID 32106613, 2020). "Hence, in addition to their known anti-cancer roles, our findings suggest the therapeutic response of tumors to inhibitors of PGD and G6PD will be amplified at acidic pHi." (PMID 30065243, 2018). "TAp73 expression is associated with an increased serine/glycine synthesis, production of NADPH and GSH in different cancer models, and glutaminase-2 (GLS-2) and glucose-6-phosphate-dehydrogenase (G6PD) metabolic enzymes have been described as direct TAP73 targets." (PMID 29733853, 2018). "Since pentoses are required for DNA synthesis, it is not surprising that metabolic changes leading to increased G6PD expression occur in different cancers, including HCC." (PMID 28553614, 2017).
cancer (continued). "In this regard, G6PD, CA I, II or GST inhibitors may be useful because of their several applications, in particular for the treatment of glaucoma, epilepsy, cancer and as diuretics." (PMID 28930221, 2017). "Data analyses based on multiple bioinformatics tools produced a large body of biologically meaningful information, and revealed a number of genes such as SAMHD1, G6PD, GPD2 and ENO1, which have been reported to be related to immune response, blood biology, bone remodeling, and cancer respectively." (PMID 27878450, 2017). "Several researchers consider a high G6PD activity in tumors as an independent negative prognostic marker in cancer." (PMID 27872579, 2016). "There is active research looking for more potent, less androgenic DHEA analogs and non-steroid G6PD inhibitors for cancer treatment." (PMID 25560241, 2015). "Therefore, increase in G6PD expression and PPP flux increase intracellular GSH levels and reduce drug accumulation in cancer cells." (PMID 24738035, 2014). "Thus, enzymatic down-regulation of glucose-6-phosphate dehydrogenase (G6PDH) and TKT1 is required to effectively arrest growth rate for cancer cells in animals." (PMID 20811631, 2010). "Collectively, they suggest that targeting the G6PD-HIF-1α loop aligns with the emerging paradigm of combinatorial strategies against multiple tumor microenvironment components and provide both novel insights and a theoretical foundation for therapeutic strategies aimed at targeting cancer stemness." (PMID 41050691, 2025). "Several enzymes in the oxidative (e.g., G6PD) as well as non-oxidative (e.g., TALDO1, TKT) phases of pentose phosphate pathway was highly expressed in pRCC type 1, associated with increased demand for ribonucleotides in the rapidly proliferating cancer cells." (PMID 38703764, 2024). "Unfortunately, there is a lack of pan-cancer analysis of G6PD." (PMID 37601657, 2023). "Our work implies that GSTP1 plays a dominant role linking G6PD and SRC to form a “signalosome” that provides a basis, under metabolic stresses, for robust cancer cell proliferation upon lactic acid signaling, which could regulate many aspects of cellular metabolism." (PMID 37491277, 2023). "In a variety of cancers, G6PD is essential for maintaining low levels of reactive oxygen species(ROS) and reduced glutathione/oxidized glutathione ratio(GSH/GSSG) balance in that G6PD creates NADPH to maintain redox balance and promotes tumor cell proliferation and inhibits cell apoptosis." (PMID 38111012, 2023). "HKs (HK1 and HK2), PFK1 and PFK2, G6PD, pyruvate kinase, phosphoglycerate dehydrogenase (PHGDH), lactate dehydrogenase, phosphoglycerate kinase 1 (PGK1), enolase (ENO), isocitrate dehydrogenase (IDH), and glucose transferase (GLUT) serve as ideal pharmacological targets to treat cancer." (PMID 36984785, 2023). "In actuality, there is still a lack of G6PD pan-cancer analysis." (PMID 37601657, 2023). "Similarly to G6PD, PFK1 was also found to undergo O-GlcNAcylation in cancer cells." (PMID 36359905, 2022). "Whether G6PD contributes to the development of cancer independent of its metabolic and enzyme function needs to be further discussed." (PMID 35207558, 2022). "However, the entire mechanism by which G6PD inhibition affects cancer progression is not fully elucidated, and until the present, there are no conclusive studies demonstrating why G6PD is essential for cancer cells." (PMID 34572981, 2021). "G6PD is the rate-limiting enzyme of PPP flux, which may facilitate cancer cell invasion." (PMID 34235156, 2021). "Upregulation of the G6PD level or activity is often observed in many kinds of cancer, suggesting that PPP may represent an important target for regulating the redox homeostasis in cancer." (PMID 34205698, 2021). "This raises the possibility of whether or not G6PD can serve as a therapeutic target concomitant with existing anticancer drug to tackle cancer resistance." (PMID 31500396, 2019).